FLT3 (fms related receptor tyrosine kinase 3)
Diseases named in the same sentence as FLT3 in open-access papers (continued):
Sharing a sentence is not in itself a finding about the gene and the disease.
myelodysplastic syndrome (continued). "Of the 107 patients evaluated, 19 (male, n = 15; female, n = 4) had AML secondary to myelodysplastic syndrome (MDS); all but one was FLT3-ITD+, 14 had refractory disease and five had relapsed AML." (PMID 35523692, 2022). "Internal tandem duplication (ITD) mutations of the juxtamembrane domain coding sequence of the FLT3 gene have been identified in 17% to 34% of patients with AML and 5% of patients with myelodysplastic syndrome." (PMID 22970245, 2012). "The most prevalent form of mutant FLT3, present in approximately 20–25% of AML patients and less than 5% of myelodysplastic syndrome (MDS) patients, occurs as internal tandem duplications (ITD) within the juxtamembrane domain." (PMID 21980431, 2011). "We observed these cell cycle alterations and the induction of the subG1 fractions similarly in MOLM-13 cells (express FLT3-ITD and wild-type FLT3, from a 20-year-old man with AML cells after initial myelodysplastic syndrome) that we treated with 2 nM AC220 ± 2 nM FK228." (PMID 34665271, 2022). "FLT3 mutations have also been seen in myelodysplastic syndrome (MDS) in about 3–5% of newly diagnosed patients and in MDS patients without FLT3 mutations, they sometimes appear when these patients progress to AML." (PMID 24696688, 2014). "Molecular testing for FLT3, NPM1, and CEBPA was not performed, given the picture of antecedent myelodysplastic syndrome (MDS)." (PMID 26114018, 2014).
acute promyelocytic leukemia (50 papers, 2011 to 2025). An aggressive form of acute myeloid leukemia (AML), characterized by arrest of leukocyte differentiation at the promyelocyte stage, due to a specific chromosomal translocation t(15;17) in myeloid cells. "Present in 12–38% of acute promyelocytic leukemia, FLT3-ITD has been associated with high white blood cell counts (WBCs), the short PML-RARα breakpoint cluster region 3 (bcr3) isoform, and microgranular variant M3 (M3v) APL." (PMID 33800974, 2021). "The expression of SLAP is increased in patients with acute promyelocytic leukemia (APL) carrying Flt3-ITD mutation as compared to the Flt3-WT." (PMID 26339145, 2015). "Historically, except for acute promyelocytic leukemia (APL), conventional chemotherapy (“3+7”) alone was the standard strategy for FLT3-mutated AML." (PMID 36185253, 2022). "Around 12–38% of acute promyelocytic leukemia (APL) patients carry the FLT3-ITD mutation, which has been associated with several poor-prognosis indicators such as high white blood cell counts, M3v variant morphology, and the bcr3 isoform." (PMID 33800974, 2021). "Several subtypes of AML, like fms-related receptor tyrosine kinase 3 (FLT3)-mutated AML, AML harboring the translocation AML-ETO, acute promyelocytic leukemia, and trisomy 21-acute megakaryocytic leukemia, are associated with high levels of miR-125b." (PMID 38255226, 2024). "Reports 2-4 have shown that arsenic trioxide (ATO) alone or in combination with all-trans retinoic acid (ATRA) improved prognosis in acute promyelocytic leukemia (APL) with FLT3-ITD." (PMID 32284743, 2020). "Scientific understanding of the AML biology has led to the development of targeted treatment approaches, i.e., the all-trans retinoic acid (ATRA) treatment for acute promyelocytic leukemia (APL) that carries the PML-RARα translocation or the use of FLT3 kinase inhibitors in FLT3-mutated cases." (PMID 32110991, 2020). "Except for acute promyelocytic leukemia (APL) and—recently—FLT3 mutated AML, the substantial (genetic) heterogeneity of AML so far has had only a moderate impact on the choice of therapy." (PMID 30275528, 2018). "Hyperthyroidism complicated with leukemia is even rarer, particularly acute promyelocytic leukemia (APL) with FMS-like tyrosine kinase 3-internal tandem duplication (FLT3-ITD)." (PMID 24396459, 2014). "Other studies were devoted to analyze the cooperation between PML-RARA and FLT3-ITD in promoting the development of acute promyelocytic leukemia (APL)." (PMID 23936658, 2013). "So far, this concept has been successful by using all-trans retinoic acid (ATRA) and/or arsenic trioxide in the therapy of acute promyelocytic leukemia (APL), as well as by introducing midostaurin and enasidenib in the therapy of AML with FLT3 and IDH2 mutations, respectively." (PMID 30728457, 2019). "Somatic mutations of FLT3 are among the most common mutations in AML, with a prevalence of 10 to 20% in children and AYAs with AML, including acute promyelocytic leukemia (APL)." (PMID 38473358, 2024). "However, there are certain leukemia cases, for instance, acute promyelocytic leukemia (APL) patients with mutations in PML‐RARα, NPM1, and FLT3‐ITD fusion genes, and CML patients with BCR‐ABL1 gene, show significant resistance to chemotherapeutic drugs, leading to disease progression and even death." (PMID 36705414, 2023). "The CD33 expression level appears linked to the differentiation status of the leukemia clone (e.g., high level is seen in acute promyelocytic leukemia; APL), the cytogenic profiles and to certain mutations, such as NPM1 and FLT3/ITD." (PMID 35690610, 2022). "CD33 is highly expressed in acute promyelocytic leukemia (APL), NPM1-mutated AML, and FLT3/ITD mutated AML, whereas expression is usually low in leukemias with core-binding factor translocations." (PMID 36276074, 2022).
acute promyelocytic leukemia (continued). "Among the three overexpressed proteins for high Ara-C LC50 level, CTSF was shown to have a function in azurophil granules and was found to be overexpressed in acute promyelocytic leukemia (APL) FLT3-ITD." (PMID 34202615, 2021). "The association of FLT3 mutations with white blood cell (WBC) counts at diagnosis and early death was studied in patients with acute promyelocytic leukemia (APL)." (PMID 31492033, 2019). "In accordance with the two-hit hypothesis of leukemic transformation, FLT3-ITD expression in mouse bone marrow cells expressing a promyelocytic leukemia (PML)/retinoic acid receptor (RAR) α fusion protein of acute promyelocytic leukemia (APL) caused accelerated malignant transformation." (PMID 21453545, 2011). "The negative effect of FLT3 mutations was also observed in patients with acute promyelocytic leukemia (APL)." (PMID 33042924, 2020). "Among AML subtypes, acute promyelocytic leukemia had the lowest levels of IL-8 secretion, while FLT3-ITD AML had the highest IL-8 levels, which can predict for poor prognosis in FLT3-ITD AML." (PMID 29181334, 2017). "For example, only the combination of two master modifiers, all-trans retinoic acid and arsenic trioxide, abrogate the negative prognostic impact of FLT3-ITD in promyelocytic leukemia, whereas all-trans retinoic acid alone may not impede the negative influence of FLT3-ITD." (PMID 31921665, 2019). "The significance of FLT3-ITD in acute promyelocytic leukemia (APL) is not well-established." (PMID 33800974, 2021). "Moreover, RHOBTB2 expression was increased in non-acute promyelocytic leukemia (APL) subtypes, patients without FLT3 mutation and PML/RAR fusion, and imparted a positive correlation with the expression of FLT3, FHL1, and RUNXs." (PMID 34074803, 2021).
myeloid leukemia (45 papers, 2012 to 2026). A clonal proliferation of myeloid cells and their precursors in the bone marrow, peripheral blood, and spleen. "In this review, we summarize human myeloid leukemia cell lines expressing FLT3 mutations and current therapies for FLT3-mutant AML." (PMID 41287669, 2025). "In this review, we summarize the human myeloid leukemia cell lines that express mutated FLT3 and the effect of several drugs on these cell lines." (PMID 41287669, 2025). "There are several human myeloid leukemia cell lines available, but only a few contain activating mutations in FLT3." (PMID 41287669, 2025). "Aberrant activation of FLT3 due to mutation or epigenetic deregulation can be oncogenic, contributing to the pathogenesis of myeloid leukemia." (PMID 38216972, 2024). "Sorafenib, a kinase inhibitor, offers hope for the treatment of refractory solid tumors and refractory myeloid leukemia in children, especially with the presence of the FLT3-ITD mutation." (PMID 35875115, 2022). "Here, we report the successful generation of the first (to our knowledge) cellular model with the FLT3-ITD mutation in a human myeloid leukemia cell line, K562, using the CRISPR-Cas9 system." (PMID 34035227, 2021). "As another example, 115 myeloid leukemia patients in the US are expected to be of type HLA-A*02:01 and carry the FLT3:D835Y mutation." (PMID 31775766, 2019). "Recently, the use of metformin has been combined with tyrosine kinase inhibitors (imatinib, sorafenib), and it has been effective in improving responses in cases of not only chronic myeloid leukemia but also myeloid leukemia with mutations in FLT3/ITD." (PMID 30176891, 2018). "Here, we examine the role of Flt3 in the pathogenesis of MLL-rearranged myeloid leukemias by transducing two MLL fusion genes into Flt3-deficient bone marrow cells." (PMID 23977266, 2013). "However, FLT3 mutations are found mainly in myeloid leukemias and mouse models have shown that such mutations predominantly confer a myeloproliferative rather than lymphoproliferative disease." (PMID 28538663, 2017). "Although FLT3 activating mutations appear to be primarily restricted to myeloid leukemias in patients, wildtype FLT3 is known to be expressed in lymphoid precursors and is expressed at low levels in nearly 100% of B-cell ALLs, suggesting a role for the receptor in early B-cell development." (PMID 22643831, 2012). "Integrative analysis identified 570 genes upregulated at both the eccDNA and mRNA levels, including myeloid leukemia-related genes (e.g., FLT3, RUNX1, and CD33) and oncogenes." (PMID 41278279, 2025). "Only a few human myeloid leukemia cell lines express mutated FLT3, despite approximately one-third of patients with AML having a mutation in FLT3." (PMID 41287669, 2025). "This gene set was heavily enriched with myeloid leukemia drivers (e.g., FLT3, RUNX1, CD33) and other tumor-promoting genes, providing a direct mechanistic link between eccDNA presence and the transcriptional dysregulation that fuels AML." (PMID 41278279, 2025). "In this review, we aim to provide clinicians and scientific researchers with a basic science understanding of human myeloid leukemia cell lines and an understanding of the implications of FLT3 signaling inhibition." (PMID 41287669, 2025). "Our aim in this review is to provide clinicians with a basic science understanding of human myeloid leukemia cell lines and to provide scientific researchers with the clinical implications of FLT3 signaling inhibition." (PMID 41287669, 2025). "We knocked out CBL in K562 cells, an immortalized myelogenous leukemia cell line overexpressing FLT3, and stimulated these cells with FLT3LG at various time points." (PMID 39403923, 2024). "Cabozantinib is a tyrosine kinase inhibitor (TKI) that exhibits substantial activity against specific myeloid leukemia cell lines with FLT3-internal tandem duplication (ITD) or AML1-ETO/KITmt mutations, including MV4-11, Molm13, and Kasumi-1 cells." (PMID 34944685, 2021).
myeloid leukemia (continued). "Myeloid leukemia driven by Flt3 activation appears to require the differentiation block mediated by Flt3 inhibition of C/EBPα." (PMID 34736527, 2021). "To get further insights into miR-342 expression in myeloid leukemia, we analyzed a small RNA sequencing data set of AML patients, grouped based on the mutational status of the AML driver gene FLT3, in comparison to healthy controls (n = 17)." (PMID 34021250, 2021). "p90RSK2, which is hyperactivated in diverse myeloid leukemia cell lines, is an essential signaling kinase regulating cell proliferation and survival in myeloblasts carrying FMS-like tyrosine kinase 3-internal tandem duplication (FLT3-ITD)." (PMID 33199836, 2021). "In this study, we generated a cellular model of the FLT3-ITD mutation using the CRISPR-Cas9 system and a human myeloid leukemia cell line, K562." (PMID 34035227, 2021). "Taken together, our data suggested that genetically modified FLT3-ITD knock-in human myeloid leukemia K562 cells upregulated CD52 expression via activation of STAT5, and alemtuzumab showed an antitumor effect via induction of ADCC in K562–FLT3ITD/WT cells." (PMID 34035227, 2021). "Additional RAS-signaling pathway activation in form of an internal tandem duplication of Fms Related Receptor Tyrosine Kinase 3 (FLT3-ITD), frequently detected in AML and associated with a worse prognosis, resulted in aggressive lympho-myeloid leukemia." (PMID 32650416, 2020). "Taken together, our results support the notion that mutant CBL‐expressing myeloid leukaemias are highly sensitive to available FLT3 inhibitors and that this effect can be significantly augmented by optimum inhibition of SYK kinase." (PMID 31943762, 2020). "In the present study, the FLT3-ITD mutation rate was significantly higher in patients with monocytic leukemia, who have a poorer prognosis, than in patients with granulocytic leukemia." (PMID 31434952, 2019). "Comparatively, the myeloid leukemia cell line MOLM14 (harboring a heterozygous FLT3 ITD mutation), which is a well-established model to test FLT3 tyrosine kinase inhibitors, was treated with crenolanib." (PMID 29137311, 2017). "To validate the clinical data, we either overexpressed or depleted FLT3-ITD in human myeloid leukaemia cell lines." (PMID 23929599, 2013). "The development of an undifferentiated myeloid leukemia in this model, also has implications for the role of FLT3 in the inhibition of myeloid differentiation." (PMID 22643831, 2012). "Third, integrative analysis identified 570 genes upregulated at both the eccDNA and mRNA levels, including myeloid leukemia drivers (FLT3, RUNX1, CD33) and oncogenes (MAP2K2/3, LINC00539), mirroring the “eccDNA–oncogene amplification” axis observed in solid tumors." (PMID 41278279, 2025). "Hhex expression, in combination with a mutant form of additional sex combs-like 1 (Asxl1) an epigenetic modulator often mutated in myeloid leukaemia, was also found to enhance Runx1-ETO and Flt3-ITD-driven myeloid leukaemia via upregulation of Myb and Etv5 in mice." (PMID 37398663, 2023). "Therefore, activating mutations in FLT3, primarily the FLT3-internal tandem duplication (FLT3-ITD), was used as a prognostic marker especially in myeloid leukemia; however, in ALL, the prognostic relevance of FLT3 mutations is less clear." (PMID 36407352, 2022). "However, when this mutation is combined with the FLT3/ITD knock-in mutation, mice develop strictly minimally differentiated myeloid leukemias." (PMID 22643831, 2012). "Therefore, it may be possible to improve the outcome of cases with FLT3-ITD myeloid leukemia using alemtuzumab as a GVHD prophylaxis for patients undergoing allogeneic hematopoietic stem cell transplantation." (PMID 34035227, 2021). "Patients with non-APL myeloid leukemia with FLT3-ITD mutations have a poor prognosis." (PMID 31492033, 2019).
myeloid leukemia (continued). "Apart from providing further evidence and a potential mechanism for the presence of FLT3-ITD mainly in myeloid leukemias, this study also provides some support for the hypothesis of an instructive role of growth factor receptor signaling in early hematopoiesis." (PMID 28538663, 2017). "The result further revealed that the compounds exhibited cytotoxic activity against both subtypes of myeloid leukemia cells, MV-4-11 and MOLM-13, which are highly dependent on FLT3 signalling for survival and proliferation." (PMID 41286812, 2025). "In this study, we tested Fes inhibitors from three different chemical classes for their growth-suppressive activity against Flt3-ITD+ myeloid leukemia cell lines (MV4-11, MOLM-13 and MOLM-14) vs. myeloid cells with wild-type Flt3 (THP-1)." (PMID 28727840, 2017). "Similar to FLT3-ITD-transformed cells, cells containing Bcr-Abl, AML1-ETO and N-RasE12, all of which regulate the proliferation of myeloid leukemia cells, exhibit increased p21 expression." (PMID 27387666, 2016). "To further investigate Flt3 regulation in uncommitted cells, we performed a series of X-ChIP experiments in HPC7 and compared the results to our previous findings in myelogeneous leukaemia." (PMID 26382271, 2015). "For these studies, we used the human myeloid leukemia cell line TF-1, which expresses endogenous Fes but not Flt3." (PMID 28727840, 2017). "In addition to the mature LCs and the PDCs, FLT3 mRNA was expressed by HPCs and committed GMPs and in several AML lines, consistent with its involvement in myeloid leukemia." (PMID 25717144, 2015). "Our findings demonstrate that myeloid leukemias induced by MLL-rearranged genes are not dependent upon Flt3 signaling." (PMID 23977266, 2013). "Most FLT3 inhibitors possess antitumor activity as they can block the activated STAT5 pathway in AML cells with FLT3-ITD, and combination approaches with quizartinib or midostaurin and other anti-cancer drugs were mainly studied in myeloid leukemia and not solid tumors." (PMID 31554189, 2019).